SOCS5 (suppressor of cytokine signaling 5)
Diseases named in the same sentence as SOCS5 in open-access papers (continued):
Sharing a sentence is not in itself a finding about the gene and the disease.
infection (11 papers, 2011 to 2024). The state of being infected such as from the introduction of a foreign agent such as serum, vaccine, antigenic substance or organism. "This is further supported by the increased phosphorylation of the PI3K downstream substrate AKT in the lungs of Socs5-deficient mice during infection." (PMID 28195529, 2017). "In contrast to infection with H3N2, H1N1 and H11N9, infection with the highly pathogenic avian virus H5N1 dramatically suppressed Socs5 expression relative to the media control." (PMID 28195529, 2017). "PI3K inhibition (BKM-120 or Wortmannin) reduced viral titres in primary mouse and human epithelial cells, with SOCS5-deficient cells retaining a significantly higher level of infection compared to wild-type cells." (PMID 28195529, 2017). "Notably, the difference in PI3K p110α expression in lungs was detected prior to infection, suggesting that exaggerated activation of this pathway might underlie the increased viral susceptibility in the Socs5−/− mice." (PMID 28195529, 2017). "Our results demonstrated that the infection with RBSDV triggered SOCS5-mediated apoptosis to benefit viral replication." (PMID 36928081, 2023). "Many reports have shown that miRNA regulate the JAK/STAT signaling pathway through inhibition of SOCS5 in response to pathogen infection." (PMID 36471418, 2022). "In contrast, MG down-regulated gga-miR-365-3p in cells at the late stage of infection, resulting in an increase in SOCS5 expression." (PMID 36471418, 2022). "In our study, we indicated that SOCS5 was a direct target of miR-221-3p in DEF upon DTMUV infection, and knockdown of the expression of SOCS5 enhanced DTMUV replication." (PMID 32373087, 2020). "Socs5 mRNA was expressed in uninfected mouse lungs and was significantly upregulated at day two post-infection; by comparison, Socs4 was expressed at very low levels even during infection." (PMID 28195529, 2017). "This suggests that in vivo, SOCS5 regulates PI3K-independent EGFR effects that are required for restraint of the infection." (PMID 28195529, 2017). "Pro-inflammatory cytokines and chemokines were elevated in the bronchoalveolar lavage (BAL) from Socs5−/− mice, day two post-infection." (PMID 28195529, 2017). "Reduced SOCS5 expression in primary human epithelial cells also resulted in increased viral HA protein within 2 h of infection, indicating that early events in the viral life cycle such as viral entry and trafficking are enhanced." (PMID 28195529, 2017). "Starting from the early infection stage (12 hpi), SOCS2 and SOCS5 show marked increasing trend in Asx and this trend persists throughout the entire infection period." (PMID 21901105, 2011). "In this study, we found that gga-miR-365-3p was significantly upregulated in infected cells compared with normal cells at the early stage of infection (8 h), but significantly decreased at the late stage of infection (24 h), whereas the expression level of SOCS5 was the opposite." (PMID 36471418, 2022). "We speculated that DTMUV induced miR-221-3p expression via related molecular pathways during DTMUV infection, and then miR-221-3p targeted SOCS5 and inhibited its expression, which thus might enhance EGFR activity." (PMID 32373087, 2020). "Both Asibi and YF-17D up-regulated SOCS5 expression by ~1.5-folds during the early phase of infection in HeLa cells (3–12 hpi) but levels decreased below the expression in control cells in the late phase of infection (24–48 hpi)." (PMID 32722523, 2020). "Conversely, SOCS5 levels in lung cells of smokers with COPD remained low after infection." (PMID 28195529, 2017). "At day two post-infection, these changes were apparent at a global level in Socs5−/− lungs, with quantitative proteomic analysis showing increased expression of neutrophil proteins and neutrophil chemotactic proteins, in addition to detection of viral NS1, HA and NP proteins." (PMID 28195529, 2017).
infection (continued). "When a low MOI was used in the presence of trypsin (to ensure multiple rounds of replication and release from the cells), Socs5−/− mAECs showed elevated viral titres 24 and 48 h post-infection, confirming the reduced capacity of Socs5−/− mAECs to restrain viral replication." (PMID 28195529, 2017). "The experiments show that mice lacking the gene that encodes SOCS5 were more susceptible to infection by the influenza virus, had more severe symptoms of disease and increased amounts of virus in their lungs." (PMID 28195529, 2017). "At day one post-infection, the expression of EGFR and PI3K p85 and p110α subunits were increased in Socs5−/− lungs." (PMID 28195529, 2017). "In combination with the results above, SOCS5 showed a negative correlation with the kinetic expression profiles of miR-26a at different time points post-infection and different MOIs." (PMID 31861450, 2019). "Depletion of SOCS5 also resulted in increased viral-induction of EGFR phosphorylation, and the changes in EGFR and PI3K again correlated with increased viral HA levels 2 h post-infection." (PMID 28195529, 2017). "Mice lacking Socs5 lost significantly more body weight following PR8 infection compared to wild-type BALB/c mice." (PMID 28195529, 2017). "We found that SOCS1 and SOCS3, but not SOCS5, mRNA transcripts are up-regulated at early time points following infection of IC-21 monolayers with SG-MCMV." (PMID 28182772, 2017). "In contrast, type I and type III IFNs were not increased in Socs5−/− lung homogenates, whilst the levels of IFNα, β and λ appeared to be modestly decreased at day one post-infection." (PMID 28195529, 2017). "Of the 14 Th1 response genes tested, the expression levels of 8 genes (IL2, IFNG, CSF2, TLR4, CD4, IRF1, SOCS5 and STAT4) were significantly elevated at 2 weeks and several of these (IL2, IFNG, TLR4, CD4 and STAT4) had similar expression levels at 4 and 8 weeks post-infection." (PMID 23448601, 2013). "We report that infection of IC-21 mouse macrophages with MCMV propagated through the salivary glands of BALB/c mice, but not from tissue culture in C57BL/6 fibroblasts, transiently stimulates SOCS1 and SOCS3 mRNA transcripts, but not SOCS5 mRNA." (PMID 28182772, 2017).
SOCS5 also shares sentences with these, for which no sentence is quoted: colorectal cancer (4 papers); atopic dermatitis (2); non-small cell lung carcinoma (2); acute lymphoblastic leukemia (1); anaplastic thyroid cancer (1); bladder cancer (1); bronchiectasis (1); cardiovascular disease (1); chronic myeloid leukemia (1); encephalitis (1); endometrial carcinoma (1); esophageal squamous cell carcinoma (1); gastric cancer (1); Hypertension (1); immune disease (1); kidney diseases (1); lentivirus infection (1); lung (1); lung disease (1); lung injury (1); melanoma (1); multiple sclerosis (1); Obesity (1); postmenopausal osteoporosis (1); steatosis (1); triple-negative breast carcinoma (1); type 2 diabetes mellitus (1); uveitis (1).